ENSG00000258539 (novel transcript, METTL10-FAM53B readthrough)
Gene: Protein-coding gene on chromosome 10 (124,617,080 to 124,791,727, reverse strand). Ensembl gene ENSG00000258539.
Genetic constraint (gnomAD): Missense variants: 105 observed, 137.9 expected, observed/expected ratio (o/e) 0.76, 90% interval 0.65 to 0.89. Synonymous variants: 39 observed, 50.56 expected, observed/expected ratio (o/e) 0.77, 90% interval 0.6 to 1.01.